NPY1R (neuropeptide Y receptor Y1)
Description:
Receptor for neuropeptide Y (NPY) and peptide YY (PYY). Can also bind with high affinity [Leu-31, Pro-34]NPY, an analog of NPY modified at residues 31 and 34 of the mature form, while having virtually no affinity for pancreatic polypeptide (PP/PPY) at physiological concentrations. NPY or PYY binding induces adenylate cyclase-inhibiting G protein-coupled receptor signaling, resulting in inhibition of cAMP production. Receptor activation by ligands also leads to an increase of intracellular Ca(2+) levels. As a receptor for NPY, it is involved in the regulation of eating behaviour and NPY-induced stimulation of food intake (By similarity). Involved in the regulation of colonic antisecretory tone, and colonic contractility (By similarity).
Synonyms: NPY1-R; NPYR
Tractability: Small molecule: a structure with a bound ligand is known; a high-quality ligand is known; it belongs to a druggable protein family. Antibody: its Gene Ontology location is reachable by antibodies, with high confidence; UniProt places it where antibodies can reach, with medium confidence; UniProt predicts a signal peptide or a membrane-spanning region. PROTAC: a small molecule that binds it is known.
Target class: Neuropeptide Y receptor; Peptide receptor (family A GPCR); Membrane receptor; Family A G protein-coupled receptor; Short peptide receptor (family A GPCR)
Chemical probes: BIBO3304 (high quality), BIBP3226 (high quality), BIBP3226, CHEMBL329536
Safety:
Unwanted effects reported when the protein is acted on. In parentheses: how it was acted on, where the effect was seen, and who reports it.
anxiolytic effects (activation; cardiovascular system, nervous system; source: Urban et al. (2012))
atherosclerosis (activation; cardiovascular system, nervous system; source: Urban et al. (2012))
decreased eating (inhibition, acute dosing; nervous system, immune, gastrointestinal; source: Lynch et al. (2017))
decreased pain (activation, acute dosing; nervous system, immune, gastrointestinal; source: Lynch et al. (2017))
decreased/increased inflammation (activation, acute dosing; nervous system, immune, gastrointestinal; source: Lynch et al. (2017))
increase in anxiety-related effects (inhibition; cardiovascular system, nervous system; source: Urban et al. (2012))
restenosis (activation; cardiovascular system, nervous system; source: Urban et al. (2012))
smooth-muscle cell growth (activation; cardiovascular system, nervous system; source: Urban et al. (2012))
stimulation of feeding behavior (activation; cardiovascular system, nervous system; source: Urban et al. (2012))
stroke (activation; cardiovascular system, nervous system; source: Urban et al. (2012))
vasoconstriction (activation; cardiovascular system, nervous system; source: Urban et al. (2012))
vasodilation (especially venous) (inhibition; cardiovascular system, nervous system; source: Urban et al. (2012))
vasodilation in subcutaneous arteries (activation; cardiovascular system, nervous system; source: Urban et al. (2012))
Gene: Protein-coding gene on chromosome 4 (163,323,962 to 163,344,852, reverse strand). Ensembl gene ENSG00000164128.
Subcellular location: Cell membrane
Pathways (Reactome):
Signal Transduction: G alpha (i) signalling events; Peptide ligand-binding receptors
Gene Ontology:
Molecular function: neuropeptide receptor activity; protein binding; neuropeptide Y receptor activity; peptide YY receptor activity; G protein-coupled receptor activity; pancreatic polypeptide receptor activity
Biological process: adenylate cyclase-inhibiting G protein-coupled receptor signaling pathway; outflow tract morphogenesis; G protein-coupled receptor signaling pathway, coupled to cyclic nucleotide second messenger; neuropeptide signaling pathway; positive regulation of eating behavior; G protein-coupled receptor signaling pathway
Cellular component: plasma membrane; neuron projection; membrane
Genetic constraint (gnomAD): Loss-of-function variants: 8 observed, 21.13 expected, observed/expected ratio (o/e) 0.38, 90% interval 0.22 to 0.68. The upper end of that interval is the gene's LOEUF score, 0.68, which puts it in group 2 of 6, group 1 being the genes least tolerant of losing a copy. Missense variants: 302 observed, 431.6 expected, observed/expected ratio (o/e) 0.7, 90% interval 0.64 to 0.77. Synonymous variants: 157 observed, 159.06 expected, observed/expected ratio (o/e) 0.99, 90% interval 0.87 to 1.13.
Homologues: Orthologues: chimpanzee NPY1R (99% identical), macaque NPY1R (99% identical), dog NPY1R (96% identical), rabbit NPY1R (96% identical), pig NPY1R (95% identical), mouse Npy1r (93% identical), rat Npy1r (93% identical), guinea pig NPY1R (91% identical), tropical clawed frog npy1r (76% identical), zebrafish npy1r (57% identical). Paralogues in human: NPY4R2 (43% identical), NPY4R (43% identical), NPY5R (27% identical), TACR3 (27% identical), NPY2R (26% identical), TACR1 (26% identical), TACR2 (25% identical), GPR83 (25% identical), PRLHR (24% identical), MTNR1A (21% identical), PROKR2 (21% identical), MTNR1B (20% identical), and 21 more.
Diseases named in the same sentence as NPY1R in open-access papers:
NPY1R is named in the same sentence as 57 diseases in open-access papers, as found by Europe PMC text mining. Sharing a sentence is not in itself a finding about the gene and the disease. The quoted sentences say what the papers report.
breast cancer (14 papers, 2014 to 2025). A primary or metastatic malignant neoplasm involving the breast. "The association between clinicopathological variables and NPY1R transcript expression in the peripheral blood of breast cancer patients was analyzed." (PMID 25624911, 2015). "Future studies, which investigate the cellular mechanisms underlying the role of NPY1R in breast cancer are required, as this may lead to the development of drugs to target NPY1R for breast cancer treatment." (PMID 25624911, 2015). "NPY1R, a novel peripheral blood marker, is upregulated in breast cancer, promoting proliferation and migration, and is positively correlated with metastatic diseases and highly expressed in circulating tumor cells among breast cancer patients." (PMID 36148946, 2022). "This can be achieved by using [F7, P34]-NPY, a NPY1R-preferring peptide ligand, which was already successfully used to target NPY1R-positive breast cancer cells [,66,79,80]." (PMID 31918918, 2020). "Breast cancer patients with circulating cancer cells that expressed NPY1R exhibited shorter tumor-specific survival when compared with those with no NPY1R expression (P<0.01)." (PMID 25624911, 2015). "Of note, high NPY1R expression levels were detected in the lymph node metastasis group, which highlights the value of NPY1R as a predictive peripheral blood marker of lymph node metastasis in breast cancer." (PMID 25624911, 2015). "Positive NPY1R gene expression was identified in 5/10 breast cancer patient samples; however, 0/10 normal controls appeared to express NPY1R." (PMID 25624911, 2015). "In the present study, the correlation between NPY1R expression and various clinicopathological features of breast cancer patients was analyzed." (PMID 25624911, 2015). "Nested quantitative polymerase chain reaction was performed to correlate the NPY1R expression levels with the clinicopathological features of 142 breast cancer patients." (PMID 25624911, 2015). "Using this clinical threshold for marker positivity, it was observed that the positive detection rate of circulating cancer cells in 142 breast cancer patients was 44.4% (63/142) for the NPY1R gene." (PMID 25624911, 2015). "Nested qPCR was performed to determine the expression level of NPY1R in the peripheral blood of 142 clinical samples obtained from breast cancer patients." (PMID 25624911, 2015). "Of the 43 breast cancer patients, 14 patients exhibited NPY1R expression and 16 patients expressed FAM83A, however, these two marker genes were undetectable in the peripheral blood of the 20 healthy control subjects." (PMID 24932314, 2014). "Previous studies revealed that normal breast tissue expresses the Y2R subtype, whereas 85% of human breast carcinoma express NPY1R." (PMID 24932314, 2014). "Moreover, human patients with breast cancer whose circulating tumor cells were NPY1R positive exhibited decreased overall survival and the level of NPY1R also correlated with late-stage disease and lymph node metastases." (PMID 40073121, 2025). "In the present study, nested qPCF was used to identify NPY1R as a novel marker of circulating cancer cells in breast cancer patients; favorable markers are characterized by a high level of expression in breast cancer tissues but no or low expression in the peripheral blood cells of healthy patients." (PMID 25624911, 2015). "The results indicate that NPY1R may be involved in the activation of the estrogen and progesterone signaling pathway in breast carcinoma." (PMID 25624911, 2015). "Furthermore, the results indicated that estrogen is important in the upregulation of NPY1R, which in turn regulates estrogen-induced cell proliferation in breast cancer cells." (PMID 24932314, 2014). "In addition, high NPY1R expression in circulating tumor cells isolated from peripheral blood has also been shown to correlate with poor survival and lymph node metastasis in patients with breast cancer." (PMID 40073121, 2025).
breast cancer (continued). "Therefore, it was proposed that NPY1R may serve as a useful marker to predict cancer metastasis and to evaluate the prognosis of breast cancer patients." (PMID 25624911, 2015). "The upregulation of NPY1R appears to be specific to ER+ breast cancer patients and thus, a combination of multiple markers, including NPY1R, may be required to improve the sensitivity and specificity for the detection of circulating breast cancer cells." (PMID 25624911, 2015). "Taken together, these findings identify NPY1R as one of the most consistent and universal upregulated targets in ESR1 mutant breast cancer, likely driven by the constitutive activation of mutant ER and their increased binding activity at this gene locus." (PMID 39702552, 2024). "Survival analysis was performed to explore the correlation between the 4 DEGs (GFRA3, NPY1R, PTPRN2 and GABRP) with patients’ survival in over 400 breast cancer samples from TCGA database." (PMID 29423105, 2018). "The aim of the current study was to evaluate a novel tumor marker, neuropeptide Y receptor Y1 (NPY1R), for the detection of circulating cancer cells and to investigate its clinical significance in breast cancer patients." (PMID 25624911, 2015). "The three candidate markers, FAM83A, NPY1R and KRT19, were investigated further in a large cohort consisting of 142 breast cancer patients and 60 healthy controls, using the novel rapid nested PCR assay." (PMID 24932314, 2014). "In conclusion, the current study developed a novel rapid nested PCR assay to detect circulating cancer cells in the blood of breast cancer patients using a novel panel of marker genes, FAM83A, NPY1R and KRT19." (PMID 24932314, 2014). "With regard to the clinical stage, the detection rate of FAM83A and NPY1R, as well as the panel of markers, was significantly higher in patients with stage III or IV breast cancer when compared with stage I or II patients (P<0.05)." (PMID 24932314, 2014). "The positive detection rate of circulating cancer cells in breast cancer patients was 33.1 (47/142), 38.7 (55/142) and 43.7% (62/142) for the FAM83A, NPY1R and KRT19 genes, respectively." (PMID 24932314, 2014). "In breast cancer, NPY1R expression was confirmed in 85% of primary human breast carcinomas and 100% of lymph node metastases exhibiting a switch from NPY2R expression in normal breast tissue to NPY1R dominant expression during cancer progression." (PMID 40073121, 2025). "For example, two breast cancer cell lines MDA-MB-231 and MCF-7 exhibit increased motility and invasion in response to NPY, which could be blocked with pharmacological NPY1R and NPY5R antagonists." (PMID 40073121, 2025). "Neuropeptide Y receptor Y1 (NPY1R), identified as a novel peripheral blood biomarker, may predict for the prognosis and metastasis of breast cancer patients." (PMID 34113405, 2021). "The breast cancer patients with NPY1R-positive circulating cancer cells exhibited shorter tumor-specific survival compared with individuals with absent NPY1R expression (P<0.01)." (PMID 25624911, 2015). "The rapid nested PCR method was used to detect the circulating cancer cells of 142 breast cancer patients, using a panel of marker genes (FAM83A, NPY1R and KRT19), which were identified by the Digital Gene Expression Displayer Tool of the National Cancer Institute-Cancer Genome Anatomy Project." (PMID 24932314, 2014). "In addition, the current study identified a novel panel of marker genes (FAM83A, NPY1R and KRT19) for the detection of cancer cells in the peripheral blood of breast cancer patients." (PMID 24932314, 2014). "Remarkably, knockdown of NPY1R significantly inhibited the growth of T47D WT cells under E2 stimulation, as well as the ligand-independent growth of ESR1 mutant cells, underscoring the essential role of NPY1R in estrogen-dependent and ESR1 mutant breast cancer cell growth." (PMID 39702552, 2024).
breast cancer (continued). "Among them, NPY1R is the only receptor with a high incidence in human breast carcinomas, however it is unclear whether the NPY is locally synthesized in breast tissue or endogenously expressed by breast cancer cells." (PMID 35121782, 2022).
Anxiety (10 papers, 2011 to 2024). Intense feelings of nervousness, tension, or panic often arise in response to interpersonal stresses. "NPY1R is regulated by the early maternal environment and is linked to anxiety and stress reaction regulation, being related to appetite stimulation." (PMID 37630771, 2023). "After a broad analysis of altered transcripts in the mPFC of ELS mice we focused our attention on Npy1r, a G-protein coupled receptor that has been linked to maternal care and anxiety, foraging behaviors, and regulation of social behaviors." (PMID 32492699, 2020). "Our results showed that either the lack of n-3, WD transition, and/or mTBI strongly attenuated NPY1R levels, or there was a strong association between lowered NPY1R and anxiety-like behavior." (PMID 23483949, 2013). "TBI resulted in an increase in anxiety-like behavior and its molecular counterpart NPY1R, a hallmark of PTSD, but these effects were more pronounced in the animals exposed to n-3 deficient diet and switched to WD." (PMID 23483949, 2013). "Studies have demonstrated that NPY1R in the prefrontal cortex, hippocampus, and hypothalamus plays an important role in the regulation of anxiety-related behaviours." (PMID 37630771, 2023). "Using different cohorts of maternally deprived mice, we validated a significant increase in the expression of Npy1r, a receptor known to play a role in maternal care, anxiety, foraging, and regulation of group behavior." (PMID 32492699, 2020). "Regarding [i], low female expression of both Npy and Npy1r in the amygdala predicts higher anxiety only if NPY originates locally within this brain region." (PMID 28894112, 2017). "There was a positive correlation between NPY1R levels and percentage time spent in open arm (r = 0.6482, p<0.01), which is consistent with an involvement of NPY1R in anxiety-like behavior." (PMID 23483949, 2013). "We assessed levels of the Neuropeptide-Y1 Receptor (NPY1R) in the frontal cortex based on the demonstrated role of NPY on anxiety-like behavior." (PMID 23483949, 2013). "We assessed levels of NPY-1R based on its action providing resilience against anxiety and depression-like behavior, particularly throughout the frontal cortex and limbic regions." (PMID 22163304, 2011). "We previously demonstrated that conditional knockout of Npy1r gene in the excitatory neurons of the forebrain of adolescent male mice (Npy1rrfb mice) decreased body weight growth and adipose tissue and increased anxiety." (PMID 34445453, 2021). "Moreover, NPY1R is known to play a role in biological functions related to anxiety and feeding." (PMID 32492699, 2020). "Taken together, the decrease in NPY-1R and increase in GR in n-3 deficient rats may suggest that early DHA deficiency can hinder the ability to cope with challenges in adulthood, leading to anxiety-like behavior." (PMID 22163304, 2011). "In another study, the absence of anxiety-like behavior in female mice, compared with males fed a low-protein diet during development, was suggested to be due to increased methylation of the Npy1r gene in the female amygdala." (PMID 39040432, 2024). "Furthermore, it has been shown that NPY via NPY1R activation suppresses the corticotropin-releasing factor (CRF) and modulates GABAergic pathways in the CeA to regulate anxiety and alcohol-related behaviors." (PMID 36089615, 2022).